CXCR3 (C-X-C motif chemokine receptor 3)
Diseases named in the same sentence as CXCR3 in open-access papers (continued):
Sharing a sentence is not in itself a finding about the gene and the disease.
neuropathy (3 papers, 2021 to 2023). A disorder affecting the nervous system that manifests with pain, tingling, numbness, and/or muscle weakness. "Our in vitro experiments were designed to clarify the potential direct effects of CXCR2 and CXCR3 signaling on glial cells, especially since microglia play an important role in the development of neuropathy." (PMID 34681732, 2021). "Therefore, in our opinion, the modulation of CXCR3/CXCL10 signaling can bring satisfactory pain relief in neuropathy." (PMID 37570736, 2023). "It is known that at the spinal cord level, CXCL10 enhances the amplitude of spontaneous excitatory postsynaptic current and increases NMDA-/AMPA-induced currents via CXCR3; these results support a role for the CXCL10/CXCR3 axis in facilitating excitatory synaptic transmission in neuropathy." (PMID 37570736, 2023). "Several studies also suggest a key role of CXCL10/CXCR3 signaling in neuropathy." (PMID 35962398, 2022). "Our studies have been conducted to identify the similarities and differences between two chemokine receptors, CXCR2 and CXCR3, in neuroimmune processes occurring during neuropathy and to determine which one may become a better target for neuropathic pain treatment." (PMID 34681732, 2021).
oral cancer (3 papers, 2020 to 2025). "MOC2 is also a murine oral cancer cell line derived from a DMBA carcinogen induced tumor in chemokine receptor 3 (CXCR3) knockout C57BL/6 mouse." (PMID 32295135, 2020). "The expression of CCR4, CXCR3, CCR2, and CCR8 was higher in highly invasive oral cancer cell lines (SCC-25, CAL-27, and FaDu) than in the less aggressive cell line (HSC-2), whereas CCL19 and P2RY14 expression showed the opposite trend." (PMID 38213736, 2024). "We further examined the expression of CCR4, CXCR3, P2RY14, CCR2, CCR8, and CCL19 in highly aggressive oral cancer cell lines and tissues." (PMID 38213736, 2024). "Specifically, these findings indicate that CCR4, CXCR3, CCR2, and CCR8 may affect the invasiveness of oral cancer cells." (PMID 38213736, 2024). "Further analysis of gene expression in clinical tissues revealed that CCR4, CXCR3, CCR2, and CCR8 exhibited higher expression in oral cancer cells of patients with metastasis compared to those without, whereas CCL19 and P2RY14 displayed the opposite trend." (PMID 38213736, 2024).
Oral leukoplakia (3 papers, 2015 to 2021). A thickened white patch on the oral mucosa that cannot be rubbed off. "Intriguingly, the infiltrated CD4+ T cells in oral leukoplakia consisted of CXCR3+ and CCR5+ Th1 cells, a major IFN-producing cell type, and CCR4+ Th2 cells were rare in the lesion." (PMID 26242181, 2015). "We previously showed that human oral leukoplakia, a premalignant oral lesion, is a Th1-dominated tumor microenvironment that shows increased CXCL9 expression and infiltration of CXCR3+ and CCR5+ cells." (PMID 33921389, 2021). "Although CCR4+ T cells were rare in normal mucosa and in leukoplakia lesions (data not shown), CXCR3+ and CCR5+ T cells abundantly infiltrated the subepithelial stroma of leukoplakia." (PMID 26242181, 2015).
osteoarthritis (3 papers, 2019 to 2025). A noninflammatory degenerative joint disease occurring chiefly in older persons, characterized by degeneration of the articular cartilage, hypertrophy of bone at the margins and changes in the synovial membrane. "C-X-C motif chemokine receptor 3 (CXCR3) expression was significantly elevated in osteoarthritis patients." (PMID 40860192, 2025).
pancreatic adenocarcinoma (3 papers, 2014 to 2022). "IP-10 and CXCR3 mRNA levels were upregulated in pancreatic adenocarcinoma of patients obtained from pancreatectomy compared to normal pancreatic tissue, in two independent groups of patients." (PMID 25415223, 2014). "Interestingly, they also showed that the MSC-dependent accumulation of tumour-initiating cells depends on the cell type, as this effect occurred in pancreatic adenocarcinomas but not in lung cancer, although both tumours express CXCR3." (PMID 35954425, 2022).
peripheral nerve injury (3 papers, 2020 to 2022). Injury to a peripheral nerve. "Our present findings further this line of research by elucidating the potential mechanistic role of CXCL10/CXCR3 signaling in the development of neuropathic pain following peripheral nerve injury." (PMID 32265928, 2020).
psoriatic arthritis (3 papers, 2019 to 2024). Joint inflammation associated with psoriasis. "The results of this study underline the role of activated CD8+ T cell effectors in psoriatic arthritis and systemic inflammatory manifestations and indicate migration of CXCR3+ T cell from the blood to inflamed joint as a downstream event in the psoritic inflammatory cascade." (PMID 31350460, 2019). "In subjects with psoriatic arthritis, increased levels of CD8+ CCR6+ T-cell effectors expressing CD69 were found in peripheral blood, and the accumulation of CXCR3+ CD8+ and CD69+T cells was also revealed in the synovial fluid of inflamed joints." (PMID 37892710, 2023).
pulmonary TB (3 papers, 2021 to 2023). "Additionally, lymphocyte populations present in the lung of pulmonary TB patients are Th1 (CD4+IFN-γ+CXCR3−), Th17 (CD4+IL-17A+CXCR3−), and Th1/Th17 (CD4+IFN-γ+IL-17A+CXCR3−)." (PMID 36009042, 2022). "However, in our study, the TB antigen-stimulated CXCR3 levels in TB-LAP patients without pulmonary TB were slightly lower but not significantly different from those in patients with pulmonary TB." (PMID 34360313, 2021).
scleroderma (3 papers, 2020 to 2024). Scleroderma is a rare autoimmune connective tissue disorder characterized by abnormal hardening of the skin and, sometimes, other organs. "Further, CXCR3-related cytokines have been shown to be necessary for the development of scleroderma." (PMID 39337619, 2024). "In a bleomycin-induced mouse model of scleroderma, with a shorter duration of bleomycin induction meant to simulate localized scleroderma/morphea, CXCL9 and CXCR3 knockout mice were protected from the development of fibrosis." (PMID 39337619, 2024). "Notably, autoantibodies against CXCR3 and CXCR4 correlate with increased lung and skin disease severity in scleroderma patients, though it is unclear exactly how these impact signaling." (PMID 33145014, 2020).
skin cancer (3 papers, 2017 to 2023). "A previous study showed that CXCR3 is a biomarker of response for checkpoint inhibitor therapy in skin cancer." (PMID 36704723, 2023). "The role of CXCR3 is more complex in skin tumors where expression of this chemokine receptor on tumor cells can assist in tumor metastasis or the suppressive microenvironment of the tumor can overcome recruited CXCR3+ effector T cells." (PMID 30320116, 2018). "In a mouse model of skin epithelial carcinogenesis promoted by DMBA/TPA, gene deletion of CXCR3 produced a lower incidence of skin tumors." (PMID 30320116, 2018). "First, hnRNP K interacts with K17 to regulate some pro-inflammatory expression, such as C-X-C chemokine, promoting skin tumour keratinoscyes to grow and invade by CXCR3 signaling pathway." (PMID 28403883, 2017). "Consequently, the skin tumor type and a better understanding of the regulation of expression of human CXCR3 isoforms on skin tumor cells and their differential responses to CXCL9/10/11 will dictate if this chemokine receptor/chemokine system can be manipulated to treat skin cancers." (PMID 30320116, 2018).
thyroid cancer (3 papers, 2018 to 2024). "However, the role of CXCR3 spliced variants and their relation with thyroid cancer and inflammation has not been addressed." (PMID 29416784, 2018). "According to transcriptome sequencing, antitumor chemokine regulatory genes (CXCR3) were upregulated, and protumor chemokine regulatory genes (CCR3, CXCL1, CXCL2, CXCL3, CXCL8, and CXCR2) were downregulated after MWA in thyroid cancer." (PMID 38779358, 2024).
acne (2 papers, 2014 to 2021). An inflammatory process of the sebaceous glands which is characterized by comedones, nodules, papules and/or pustules on the skin. "Taken together, these results indicate that CD161+ and CXCR3+ Th cells dominate in acne skin and that these cells reside in UI skin as CD69+ T cells." (PMID 34650562, 2021).
acute coronary syndrome (2 papers, 2018 to 2023). Signs and symptoms related to acute ischemia of the myocardium secondary to coronary artery disease. "The other two ligands of CXCR3, CXCL4, and CXCL4L1, are released by platelets and have been implicated in atherogenesis and acute coronary syndrome." (PMID 30619292, 2018). "Although CXCR3 could also be activated by CXCL4 and CXCL4L1, these two chemokines are released by platelets and have been implicated in atherogenesis and acute coronary syndrome." (PMID 30619292, 2018).
adenoma (2 papers, 2023 to 2024). A neoplasm arising from the epithelium. "Th1 cells, identified by the CXCR3 or IFN-gamma expression in the tissue-derived CD4+ T cells, were upregulated from adenoma to carcinoma." (PMID 38343544, 2024).
allergic contact dermatitis (2 papers, 2019). An inflammatory skin condition caused by an immune response to direct contact between the skin and an allergen. "CXCL10 has been previously shown to drive acute itch in a model of allergic contact dermatitis via CXCR3 signaling in sensory neurons, and is elevated in skin of AD patients." (PMID 31631836, 2019). "Allergic contact dermatitis not only elicited more itch- and pain-like behaviors than ICD in mice but also a greater upregulation in the expression of mRNA and protein for IL-1β, TNF-α, CXCL10, and CXCR3." (PMID 31875186, 2019).
amyloid (2 papers, 2018 to 2025). "CXCL10 seems to be implicated in the pathogenesis of AD, indeed authors showed that a deficiency in CXCR3 helped to prevent inflammation, and a lower amyloid burden and less cognitive dysfunctions have been observed in a mouse model of AD." (PMID 30092003, 2018). "In AD mice, ablation of CXCR3 (Chemokine C-X-C motif receptor 3) ameliorates amyloidosis and cognitive decline." (PMID 40699743, 2025).
amyotrophic lateral sclerosis (2 papers, 2018 to 2025). Amyotrophic lateral sclerosis (ALS) is a neurodegenerative disease characterized by progressive muscular paralysis reflecting degeneration of motor neurons in the primary motor cortex, corticospinal tracts, brainstem and spinal cord. "For example, Tregs expressing integrin protein CD11a, in the case of CK0803 for trial NCT05695521, have been used to target the CXCR3/CXCL10 axis with the aim of engaging the inflamed microglia in patients with amyotrophic lateral sclerosis (ALS)." (PMID 41246323, 2025).
anthrax (2 papers, 2010 to 2016). "For example, in a murine model of inhalational anthrax using C57BL/6 mice relatively resistant to Sterne strain infection, antibody neutralization of CXCR3 or use of CXCR3-knockout mice, and hence disruption of the ligand-receptor interaction, had no deleterious effect on survival." (PMID 26553462, 2016). "Furthermore, we show that neutralization of these CXC ligands, but not their shared cellular receptor CXCR3, in C57BL/6 mice challenged with B. anthracis Sterne strain spores significantly increases host susceptibility to inhalational anthrax." (PMID 21124994, 2010).
bladder tumors (2 papers, 2015 to 2023). "We have previously shown that CXCR3 signaling drives T cell infiltration into murine bladder tumors after intravesical ACT." (PMID 37901214, 2023). "We observed that bladder tumors uniformly expressed only low levels of CTL attracting chemokines: CCL5, CXCL9, and CXCL10 (respective ligands for CTL-expressed CCR5 and CXCR3)." (PMID 25806105, 2015).
bone cancer (2 papers, 2017 to 2022). A primary or metastatic malignant neoplasm affecting the bone or articular cartilage. "Together, these data provided evidence that CXCR3 functions in inducing the influx of Th1 cells and NK1 cells into the BM and impacts bone tumor growth." (PMID 35503658, 2022). "By contrast, the frequency of BM NK cells, GrB+ NK cells, and Th1 cells was increased by bone tumor growth in WT but not in Cxcr3–/– mice." (PMID 35503658, 2022).
chronic kidney disease (2 papers, 2015 to 2020). Impairment of the renal function secondary to chronic kidney damage persisting for three or more months. "The study aimed at flow cytometric analysis of T cell subsets with selected surface chemokine receptors (CCR4, CCR5, CCR7, CXCR3, and CXCR4) or receptor combination in peripheral blood of children with chronic kidney disease (CKD) on hemodialysis (HD)." (PMID 25866451, 2015).
chronic pancreatitis (2 papers, 2014 to 2021). A chronic inflammatory process causing damage and fibrosis of the pancreatic parenchyma. "Significantly higher levels of CXCL10 and CXCR3 are observed in PAAD specimens compared to those from chronic pancreatitis." (PMID 33681290, 2021).
chronic periodontitis (2 papers, 2014 to 2021). A chronic inflammatory process that affects the tissues that surround and support the teeth. "Gingival tissues from patients with aggressive periodontitis present higher levels of protein-1-α (MIP-1α), IFN-γ-induced protein 10 (IP-10) and its receptors CCR5 and CXCR3, and lower levels of IL-10 than tissues of chronic periodontitis patients." (PMID 25688342, 2014). "Furthermore, the interaction of NLRP3+ macrophages and structural cells through TNF-TNFRSF1A and CXCR3_CCRL19 offered us a hint of the biological function of NLRP3+ macrophages in periodontitis." (PMID 34566966, 2021).
Cirrhosis (2 papers, 2021 to 2026). A chronic disorder of the liver in which liver tissue becomes scarred and is partially replaced by regenerative nodules and fibrotic tissue resulting in loss of liver function. "To examine B cell phenotypes in D-LC caused by HBV, we performed flow cytometry using a panel of 11 markers (CD19, CD10, CD38, IgD, CD21, CD27, CCR7, CXCR3, CXCR4, CXCR5, and IL-21R) and demonstrated the changes of B cell subsets for the first time in HBV-associated advanced cirrhosis." (PMID 34248941, 2021). "CXCR3 knockdown suppresses TLR4/MyD88, BIRC, and COL1A1 expression, inhibits proliferation and migration, and promotes apoptosis, thereby attenuating cirrhosis-to-carcinoma transition." (PMID 41258710, 2026).
crescentic glomerulonephritis (2 papers, 2023). A histopathologic term for a pattern of diseases characterized by extensive crescent formation in the glomeruli; patients present clinically with rapid deterioration of renal function, and possible progression to end-stage renal failure within weeks or months. "GC has been shown to inhibit the induction of CXCL10 in tubular epithelial cells to prevent renal infiltration of CXCR3+CD4+ T cells and subsequent renal tissue damage in patents and mice with crescentic glomerulonephritis." (PMID 39619227, 2023).
Cryptococcal meningitis (2 papers, 2025). Meningeal inflammation produced by cryptococcus neoformans, an encapsulated yeast that tends to infect individuals with acquired immunodeficiency syndrome and other immunocompromised states. "Our study suggests that mortality following cryptococcal meningitis is associated with paucity of CSF CXCR3+ T cell activating chemokine CXCL10, cellular growth activating cytokine IL-2, and immune checkpoint regulatory element PD-L1." (PMID 39928682, 2025). "In the context of cryptococcal meningitis, CXCR3 is essential for lethal brain pathology but dispensable for pathogen clearance." (PMID 40985448, 2025). "18-week survival after diagnosis of cryptococcal meningitis was associated with higher CSF leukocytes at baseline with greater T helper 1 (IFN-γ, IL-2 and TNF-α cytokines), T helper 17 (IL-17A cytokine) and CXCR3+ T cell (CXCL10 chemokine) responses." (PMID 39928682, 2025).
cutaneous leishmaniasis (2 papers, 2012 to 2024). Leishmaniasis affecting the skin. "CXCR3 plays a critical role in the host defense against cutaneous leishmaniasis caused by L. major and helps the Th1 response, while CCL17 is associated with diffuse leishmaniasis and late LCL cases." (PMID 23029578, 2012). "However, CXCR3 plays a beneficial role during cutaneous leishmaniasis by promoting the recruitment of Th1 cells to the lesions." (PMID 38709823, 2024).
cyst (2 papers, 2013 to 2020). A sac-like closed membranous structure that may be empty or contain fluid or amorphous material. "When the cyst dose was increased to 50, all CXCR3 knockout (KO) mice rapidly succumbed to infection, but some WT mice also died." (PMID 24130498, 2013). "Significant increases in mRNA levels for ICOS, CXCR3, CXCR6, IL-18R1, and Chil3 were detectable during cyst elimination by perforin-dependent anticyst activity of CD8+ T cells initiated at 6 weeks after infection." (PMID 32291349, 2020).
dermatitis (2 papers, 2013 to 2019). An inflammatory process affecting the skin. "CXCR3 is primarily expressed on Th1 CD4+ T cells, CD8+ T cells, NK, and PDCs during skin inflammation, whereas CXCR3 ligands are secreted by many tissue resident cells, including dendritic cells." (PMID 31649667, 2019).
diabetic retinopathy (2 papers, 2015 to 2025). "In the present study, IP-10 was increased in the retina of mice with diabetic retinopathy, suggesting that the CXCR3/IP-10 pathway is involved in CD8+ T cell recruitment, although this requires confirmation." (PMID 40133487, 2025).
dyslipidemia (2 papers, 2024). "Additionally, the inverse associations of CXCR3+ T lymphocytes with dyslipidemia suggest their recruitment to adipose tissue by CXCL10 or CXCL11." (PMID 39109081, 2024). "Although different associations with cardiometabolic risk factors indicate disease-specific changes, overlapping pattern was found for the associations between CCR4+ T lymphocytes and vascular inflammation, CXCR4+ subsets and albuminuria as well as CXCR3+ T lymphocytes and dyslipidemia." (PMID 39109081, 2024). "Specifically, IL-17 and chemokines such as CXCR3 enhance the influence of the liver on peripheral insulin resistance by mediating liver inflammation, and promote the occurrence of NAFLD by participating in the process of metabolic syndrome." (PMID 38698841, 2024).
esophageal adenocarcinoma (2 papers, 2020 to 2022). A malignant tumor with glandular differentiation arising predominantly from Barrett mucosa in the lower third of the esophagus. "Chemokine-receptor axes like the CXCL9, -10,-11/CXCR3- are prominent in esophageal adenocarcinoma with a fold change of up to 9.5 promoting cancer cell proliferation and metastasis." (PMID 31960110, 2020).
fibrosarcoma (2 papers, 2015). A malignant mesenchymal fibroblastic neoplasm affecting the soft tissue and bone. "Using a well-characterised model of carcinogen-induced fibrosarcomas we show that the enriched tumor-infiltrating Treg population comprises largely of CXCR3+ T-bet+ ‘TH1-like’ Tregs which are thymus-derived Helios+ cells." (PMID 26433463, 2015).
gallbladder carcinoma (2 papers, 2020 to 2022). "Recent studies have shown that CXCR3 expression is significantly elevated in gallbladder cancer tissues and is closely associated with tumor metastasis and prognosis." (PMID 36479091, 2022). "They found that immuno-suppressive macrophages increased expression of CXCL10 that binds to its receptor CXCR3 on Treg cells, eliciting tumor immune resistance in ErbB-mutation gallbladder cancer." (PMID 36479091, 2022). "In the study of gallbladder cancer with ErbB pathway mutation, the interaction between CXCL10 and CXCR3 secreted by macrophages is induced, thus promoting the progression of gallbladder cancer." (PMID 36479091, 2022).